QRFPR (pyroglutamylated RFamide peptide receptor)
Description:
Receptor for the orexigenic neuropeptide QRFP. The activity of this receptor is mediated by G proteins that modulate adenylate cyclase activity and intracellular calcium levels.
Synonyms: GPR103; AQ27; SP9155
Tractability: Small molecule: a high-quality ligand is known; it belongs to a druggable protein family. Antibody: its Gene Ontology location is reachable by antibodies, with high confidence; UniProt places it where antibodies can reach, with medium confidence; UniProt predicts a signal peptide or a membrane-spanning region. PROTAC: a small molecule that binds it is known.
Target class: Membrane receptor; RF amide receptor; Family A G protein-coupled receptor; Peptide receptor (family A GPCR); Short peptide receptor (family A GPCR)
Chemical probes: CHEMBL3314362
Gene: Protein-coding gene on chromosome 4 (121,328,595 to 121,381,059, reverse strand). Ensembl gene ENSG00000186867.
Subcellular location: Cell membrane
Pathways (Reactome):
Signal Transduction: G alpha (q) signalling events; Orexin and neuropeptides FF and QRFP bind to their respective receptors
Gene Ontology:
Molecular function: G protein-coupled receptor activity; protein binding; neuropeptide Y receptor activity
Biological process: G protein-coupled receptor signaling pathway; cellular response to hormone stimulus; neuropeptide signaling pathway
Cellular component: membrane; plasma membrane
Genetic constraint (gnomAD): Loss-of-function variants: 30 observed, 26.55 expected, observed/expected ratio (o/e) 1.13, 90% interval 0.84 to 1.53. The upper end of that interval is the gene's LOEUF score, 1.53, which puts it in group 6 of 6, group 1 being the genes least tolerant of losing a copy. Missense variants: 494 observed, 502.91 expected, observed/expected ratio (o/e) 0.98, 90% interval 0.91 to 1.06. Synonymous variants: 181 observed, 184.36 expected, observed/expected ratio (o/e) 0.98, 90% interval 0.87 to 1.11.
Homologues: Orthologues: macaque QRFPR (99% identical), chimpanzee QRFPR (98% identical), rabbit QRFPR (93% identical), pig QRFPR (91% identical), guinea pig QRFPR (90% identical), dog QRFPR (87% identical), rat Qrfpr (84% identical), mouse Qrfpr (84% identical), mouse Qrfprl (78% identical), rat Qrfprl (78% identical), tropical clawed frog qrfpr (77% identical), zebrafish QRFPR (52% identical), and 2 more. Paralogues in human: NPFFR2 (25% identical), CCKAR (23% identical), NPFFR1 (23% identical), HCRTR2 (23% identical), GALR1 (22% identical), CCKBR (21% identical), HCRTR1 (21% identical), GALR3 (18% identical), AVPR1B (17% identical), FFAR4 (17% identical), AVPR1A (16% identical), GPR22 (16% identical), and 4 more.
Diseases named in the same sentence as QRFPR in open-access papers:
QRFPR is named in the same sentence as 18 diseases in open-access papers, as found by Europe PMC text mining. Sharing a sentence is not in itself a finding about the gene and the disease. The quoted sentences say what the papers report.
Obesity (3 papers, 2016 to 2024). Accumulation of substantial excess body fat. "The 26RFa/QRFPR system plays critical roles in energy homeostasis, making QRFPR an attractive drug target for treating obesity, diabetes, and eating disorders." (PMID 38830850, 2024). "Uncovering the atomic details of 26RFa recognition and regulation of QRFPR is crucial for unraveling the function of QRFPR and developing effective treatments against obesity, diabetes, and eating disorders." (PMID 38830850, 2024). "Selective agonists and antagonists of QRFPR may take effect in the treatment of metabolic imbalance (obesity, diabetes), eating disorders, and osteoporosis." (PMID 38830850, 2024). "In addition, the system of QRFPR (also known as GPR103) and its peptide ligand RFa26 is involved in the regulation of food intake in the hypothalamus, as well as in glucose metabolism and energy metabolism, and it is thought to play a role in the development of obesity." (PMID 35323646, 2022).
insulinoma (1 paper, 2017). "In addition, QRFP26 promoted insulin secretion in MIN6 insulinoma cells, in a QRFPR-dependent manner, as inhibition of QRFPR expression using specific siRNA blocked the insulinotropic effect of the peptide." (PMID 28729853, 2017). "Although initially not found in mouse and rat pancreas, expression of QRFP26/QRFP43 and QRFPR mRNA and protein was later found in human endocrine pancreas and isolated pancreatic islets, rat INS-1E β-cells, and mouse insulinoma MIN6 cells." (PMID 28729853, 2017).
prostate carcinoma (1 paper, 2023). A carcinoma that arises from epithelial cells of the prostate gland. "QRFPR, also named GPR103, activates glutamine RF−amide peptide (QRFP), is over-expressed in human prostate cancer, and stimulates the neuroendocrine differentiation and the migration of androgen-independent prostate cancer cells." (PMID 37025600, 2023).
cancer (1 paper, 2022). A tumor composed of atypical neoplastic, often pleomorphic cells that invade other tissues. "In contrast, there have been relatively few studies on QRFPR, and the relationship of this gene with cancer is not very clear." (PMID 35875087, 2022).
tumor (1 paper, 2022). "In this table we reported some of the functions of those genes (including QRFPR and TRAM1L), mostly involved in anti-tumor immune response probably to counteract the presence of several enJSRVs in these chromosomic regions." (PMID 36290220, 2022).
QRFPR also shares sentences with these, for which no sentence is quoted: autoimmune thyroid disease (2 papers); diabetes (2); type 1 diabetes (2); Alzheimer disease (1); autoimmune disease (1); celiac disease (1); eating disorder (1); Graves disease (1); Hashimoto thyroiditis (1); Hyperglycemia (1); neuroblastoma (1); rheumatoid arthritis (1); ulcerative colitis (1).